SEC31A (SEC31 homolog A, COPII component)
Description:
Component of the coat protein complex II (COPII) which promotes the formation of transport vesicles from the endoplasmic reticulum (ER). The coat has two main functions, the physical deformation of the endoplasmic reticulum membrane into vesicles and the selection of cargo molecules (By similarity).
Synonyms: KIAA0905; SEC31L1; HSPC275; HSPC334; ABP125; ABP130; HPBKS; NEDSOSB
Tractability: Antibody: UniProt places it where antibodies can reach, with medium confidence. PROTAC: UniProt records ubiquitination sites on it; ubiquitination databases record sites on it; its protein half-life has been measured.
Gene: Protein-coding gene on chromosome 4 (82,818,081 to 82,901,166, reverse strand). Ensembl gene ENSG00000138674.
Subcellular location: Cytoplasm; Cytoplasmic vesicle, COPII-coated vesicle membrane; Endoplasmic reticulum membrane; Cytoplasm, cytosol
Subcellular location (Human Protein Atlas): Cytosol; Vesicles
Pathways (Reactome):
Immune System: Antigen Presentation: Folding, assembly and peptide loading of class I MHC; MHC class II antigen presentation
Cellular responses to stimuli: XBP1(S) activates chaperone genes
Disease: Signaling by ALK fusions and activated point mutants
Vesicle-mediated transport: COPII-mediated vesicle transport
Gene Ontology:
Molecular function: calcium-dependent protein binding; protein binding; structural molecule activity
Biological process: COPII-coated vesicle cargo loading; response to calcium ion; endoplasmic reticulum organization; endoplasmic reticulum to Golgi vesicle-mediated transport; positive regulation of ER to Golgi vesicle-mediated transport
Cellular component: COPII vesicle coat; COPII-coated ER to Golgi transport vesicle; cytoplasm; endoplasmic reticulum; endoplasmic reticulum exit site; perinuclear region of cytoplasm; vesicle coat; cytosol; endoplasmic reticulum membrane; ER to Golgi transport vesicle membrane; endomembrane system
Genetic constraint (gnomAD): Loss-of-function variants: 50 observed, 116.81 expected, observed/expected ratio (o/e) 0.43, 90% interval 0.34 to 0.54. The upper end of that interval is the gene's LOEUF score, 0.54, which puts it in group 2 of 6, group 1 being the genes least tolerant of losing a copy. Missense variants: 1,096 observed, 1,285.7 expected, observed/expected ratio (o/e) 0.85, 90% interval 0.81 to 0.9. Synonymous variants: 400 observed, 446.39 expected, observed/expected ratio (o/e) 0.9, 90% interval 0.82 to 0.97.
Homologues: Orthologues: chimpanzee SEC31A (99% identical), macaque SEC31A (99% identical), rabbit SEC31A (94% identical), dog SEC31A (94% identical), pig SEC31A (93% identical), mouse Sec31a (91% identical), guinea pig SEC31A (90% identical), rat Sec31a (90% identical), tropical clawed frog sec31a (70% identical), zebrafish sec31a (62% identical), Drosophila melanogaster Sec31 (34% identical), Caenorhabditis elegans sec-31 (21% identical). Paralogues in human: SEC31B (47% identical).
Diseases named in the same sentence as SEC31A in open-access papers:
SEC31A is named in the same sentence as 28 diseases in open-access papers, as found by Europe PMC text mining. Sharing a sentence is not in itself a finding about the gene and the disease. The quoted sentences say what the papers report.
non-small cell lung carcinoma (2 papers, 2020 to 2022). A group of at least three distinct histological types of lung cancer, including non-small cell squamous cell carcinoma, adenocarcinoma, and large cell carcinoma. "SEC31A is an external component of the COPII associated with the pathogenesis of non-small cell lung cancer." (PMID 36290392, 2022).
developmental delay (1 paper, 2025). "SEC31A-related neurodevelopmental disorder (Halperin–Birk syndrome) was recently identified in two siblings who shared the phenotype of profound developmental delay, structural brain defects, spastic quadriplegia with multiple contractures, seizures, dysmorphism, and optic nerve atrophy." (PMID 40508110, 2025).
diabetic nephropathy (1 paper, 2023). "Other proteins found with an altered abundance in our study and known to be related to diabetic nephropathy are CTSD, FHL2, and Sec31A." (PMID 36769128, 2023).
heart failure (1 paper, 2024). Inability of the heart to pump blood at an adequate rate to meet tissue metabolic requirements. "The distinct expression patterns of Ppme1, Sec31a, and Gm56451 in MI and TAC highlight their potential as biomarkers for different types of heart failure." (PMID 39502510, 2024). "Notably, Ppme1, Gm56451, and Sec31a showed contradictory expression patterns between MI and TAC, suggesting their potential as biomarkers for MI- and TAC-induced heart failure, respectively." (PMID 39502510, 2024).
melanoma (1 paper, 2019). A malignant, usually aggressive tumor composed of atypical, neoplastic melanocytes. "With regard to the genes specifically up-regulated in the MCSP CTC fraction, the majority have been involved in metastasis (LOXL4, ST6GALNAC2, PYGL), tumour growth (PLK2, CYSTM1, GLUL), and/or melanoma biology (SEC31A, WIPI1, SKP1)." (PMID 30769764, 2019). "However, DDIT3 was up-regulated as a result of the apoptotic activity triggered by the compound HA15 in melanoma cell lines, as was SEC31A, a gene found up-regulated in MCSP CTC fractions, Altogether, the role of WIPI1 and DDIT3 may indicate common molecular mechanisms in CTC biology." (PMID 30769764, 2019).
metastasis (1 paper, 2020). The spread or migration of cancer cells from one part of the body (where they first appeared) to another. "Thus, high circ-SEC31A expression was associated with increased lymph node metastasis, higher TNM stage, and larger tumor size compared with the low circ-SEC31A expression group." (PMID 32499446, 2020).
microcephaly (1 paper, 2023). A congenital or acquired developmental disorder in which the circumference of the head is smaller than normal for the person's age and sex. "In one example, a familial case of lethal, severe microcephaly with various neurological features, the patient was found to have a unique mutation in SEC31A." (PMID 37232043, 2023).
osteoporosis (1 paper, 2024). A condition of reduced bone mass, with decreased cortical thickness and a decrease in the number and size of the trabeculae of cancellous bone (but normal chemical composition), resulting in increased fracture incidence. "Subsequently, we detected the expression of Sec24a, Sec31a, LC3‐II, and Beclin1 using immunohistochemistry, and identified that these proteins decreased during osteoporosis in rats." (PMID 39361436, 2024).
ovarian carcinoma (1 paper, 2016). A malignant neoplasm originating from the surface ovarian epithelium. "We also identified several novel hub genes that were previously unreported in ovarian cancer, such as BCL2-associated transcription factor 1 (BCLAF1), ADP-ribosylation factor-like 8B (ARL8B), and SEC31 homolog A (S. cerevisiae) (SEC31A)." (PMID 26972162, 2016).
prostate adenocarcinoma (1 paper, 2011). "In contrast with the large number of TICs found in this study, we found relatively few distant gene fusions, and experimentally verified only two novel ones in prostate adenocarcinoma: IRS2-NUFIP1 and SEC31A-C6orf62." (PMID 21261984, 2011).
sarcopenia (1 paper, 2025). Progressive decline in muscle mass due to aging which results in decreased functional capacity of muscles. "KAT2A, CTNNBIP1, GABARAPL1, SEC31A, the expression of IDI1 was highly significantly elevated (p-value < 0.01) in both the Sarcopenia and Control groups in the Sarcopenia dataset GSE8479." (PMID 41325398, 2025).
tumour (5 papers, 2017 to 2021). "Reduced circ-SEC31A expression in NSCLC decreased tumor cell proliferation, migration, invasion, and malate-aspartate metabolism." (PMID 32499446, 2020). "The in vivo xenograft mouse models using A549 cells also showed that downregulating miR-520a-5p or upregulating GOT2 restored the in vivo tumor growth ability of A549 cells after circ-SEC31A knockdown." (PMID 32499446, 2020). "Many of the hub AS events, including AS events in KIFB1, SEC31A, CAST and CLSTN1, were up‐regulated in invasive and diffuse GC tissues and were significantly related to extracellular matrix and tumour stromal score." (PMID 32939931, 2020). "The most recurrent frameshift MSI events are found in ACVR2A (51.6% of the tumours), KIAA2018 (51%), SLC22A9 (50%), ASTE1 (45%), TGFBR2 (44%), NDUFC2 (36%), LTN1 (36%) and SEC31A (36%)." (PMID 28585546, 2017). "However, there were significant differences in the circ-SEC31A expression groups regarding lymph node metastasis (negative and positive), TNM stage (I/II and III/IV), and tumor size (≤3 cm and >3 cm)." (PMID 32499446, 2020).
infection (1 paper, 2022). The state of being infected such as from the introduction of a foreign agent such as serum, vaccine, antigenic substance or organism. "SERPINE1, STX4 and SEC31A, along with RAB35, are also involved in membrane trafficking and the innate immune response, which is an important initial host response to infection of cells with Chlamydia bacteria." (PMID 35510793, 2022).
neurodevelopmental disorder (1 paper, 2025). A behavioral and cognitive disorder with onset during the developmental period that involves impaired or aberrant development of intellectual, motor, or social functions. "Our findings support the clinical correlation of SEC31A variants with neurodevelopmental disorder." (PMID 40508110, 2025). "Our study makes a valuable contribution to the understanding of SEC31A-related neurodevelopmental disorders by reporting the third case and demonstrating phenotypic variability." (PMID 40508110, 2025).
SEC31A also shares sentences with these, for which no sentence is quoted: cancer (2 papers); craniolenticulosutural dysplasia (2); acute myeloid leukemia (1); B-cell lymphoma (1); cataract (1); chylomicron retention disease (1); congenital dyserythropoietic anemia type 2 (1); juvenile myelomonocytic leukemia (1); lung adenocarcinoma (1); lung carcinoma (1); plasmacytoma (1); prostate tumor (1); renal carcinoma (1); triple-negative breast carcinoma (1).